AQP8 (aquaporin 8)
Diseases named in the same sentence as AQP8 in open-access papers (continued):
Sharing a sentence is not in itself a finding about the gene and the disease.
Constipation (7 papers, 2020 to 2025). Infrequent or difficult evacuation of feces. "In the rat constipation model, the expression of AQP8 was increased in the colon, while increased AQP3 expression was increased at the proximal but decreased at the distal." (PMID 40807605, 2025). "In human, the expressions of AQP3 and AQP8 were upregulated in patients with constipation, whereas the expressions of AQP1, AQP7, and others were downregulated." (PMID 40807605, 2025). "Treatment with Urd increased the transcription of AQP3 7.4 times and 5.8 times for AQP8 in the C3 KO model compared to the Lop-induced constipation model." (PMID 41011160, 2025). "The transcription levels of AQP3 and AQP8 genes were decreased in both constipation models treated with the Vehicle." (PMID 41011160, 2025). "PKA, AQP3, and AQP8 expression was increased by constipation induction; however, lactitol treatment decreased their expression in a concentration-dependent manner." (PMID 38998634, 2024). "In this study, the mRNA expression levels of AQP3 and AQP8 were decreased in the colonic mucosa in loperamide-induced constipation rats, and rifaximin significantly increased the expression of AQP3 and AQP8." (PMID 37960154, 2023). "The result showed that the protein levels of AQP4 and AQP8 in the colon of constipation mice were significantly higher than those in the normal group." (PMID 36687730, 2022). "We detected the expression of AQP by RT-PCR and IHC and found that the expressions of AQP4 and AQP8 in the intestines of mice in the constipation group were significantly increased." (PMID 36687730, 2022). "The results suggest that YTC decreases the expression of AQP3 and AQP8 in the colons of mice with diphenoxylate-induced constipation." (PMID 32148532, 2020). "Generally, the increased expression of AQP4 and AQP8 is observed in mouse constipation models." (PMID 36904145, 2023). "Thus, we designed to examine the effect of YTC on the expression of AQP3 and AQP8 in the colons of mice with diphenoxylate-induced constipation." (PMID 32148532, 2020). "In the constipation mouse model, the expressions of AQPs have changed, including upregulated AQP3, AQP4, and AQP8, and downregulated AQP9." (PMID 40807605, 2025). "Our results showed that AQP4 and AQP8 expression in the colon of constipation mice was significantly higher than that of normal mice, while AQP4 and AQP8 expression was significantly down-regulated in the colon of three intervention groups." (PMID 36687730, 2022). "In this study, the expression level of AQP3 and AQP8 was detected and the results showed that YTC decreases the expression of AQP3 and AQP8 in the colons of mice with diphenoxylate-induced constipation." (PMID 32148532, 2020). "The RT-PCR and immunohistochemical experiment showed that all three interventions relieved constipation by affecting aquaporins (AQP4 and AQP8), interstitial cells of Cajal (SCF and c-Kit), glial cell-derived neurotrophic factor (GDNF), and Nitric Oxide Synthase (NOS)." (PMID 36687730, 2022).
glioma (7 papers, 2017 to 2024). A benign or malignant brain and spinal cord tumor that arises from glial cells (astrocytes, oligodendrocytes, ependymal cells). "Unexpectedly, increased AQP7 and AQP8 levels were associated with better survival times in glioma, ovarian and endometrial cancers, and increased AQP11 with better survival in colorectal and breast cancers." (PMID 32679804, 2020). "Specifically, high AQP8 expression promoted the proliferation and growth of glioma to some extent, while inhibition of AQP8 expression slowed down these activities." (PMID 37280594, 2023). "Collectively, these results showed that high AQP8 expression promotes the proliferation and growth of glioma." (PMID 37280594, 2023). "The WB analysis in this study showed that Bcl-2 expression was significantly decreased in AQP8 knockdown glioma cells, whereas Bcl-2 expression was increased and Bax expression was decreased in AQP8 overexpressing glioma cells." (PMID 37280594, 2023). "AQP8 activation and knockdown in glioma A172 and U251 cells showed that, to some extent, AQP8 knockdown reduced the proliferation, migration, and invasion capabilities of glioma cells." (PMID 37280594, 2023). "This supports the idea that the effect of AQP8 on apoptosis in glioma cells is related to the Bcl-2/Bax ratio." (PMID 37280594, 2023). "Glioma cell lines were then infected with the viruses, and the effect and mechanism of AQP8 on the proliferation and growth of glioma were investigated." (PMID 37280594, 2023). "The results of flow cytometry and the Hoechst assay both supported that glioma cells overexpressing AQP8 had lower early apoptosis rates, whereas those with AQP8 knockdown had significantly higher early apoptosis rates." (PMID 37280594, 2023). "Expression of AQP8 is higher in human glioma tissues than in normal brain tissues and is positively correlated with the pathological grade of glioma, suggesting that this protein is also involved in the proliferation and growth of glioma." (PMID 37280594, 2023). "This is a preliminary suggestion that AQP8 overexpression can promote the proliferation, migration, and invasion of glioma cells, whereas AQP8 knockdown can induce their apoptosis and inhibit proliferation and growth." (PMID 37280594, 2023). "Measurements of PTEN, AKT, and p-AKT protein levels in glioma cells showed that PTEN expression was decreased as AQP8 expression was increased." (PMID 37280594, 2023). "This study aimed to investigate the mechanism and role of abnormal AQP8 expression in glioma development." (PMID 37280594, 2023). "The initial objective of this study was to infect glioma cell lines with AQP8 knock out so as to explore the effect of AQP8 on their proliferation." (PMID 35245307, 2022). "Thereafter, U251 and A172 cell lines were infected with the contructed AQP8 knock-out viruses and cultured routinely for the observation of the effect of AQP8 on glioma growth and cell proliferation." (PMID 35245307, 2022). "However, previous studies have shown that the AQP8 expression level is abnormally high in human gliomas, especially glioblastoma." (PMID 37280594, 2023). "Increased AQP8 expression may promote glioma proliferation by mediating ROS levels, regulating the levels of PTEN/AKT and other downstream proteins, and forming a new redox equilibrium state in cells." (PMID 37280594, 2023). "The AQP8 overexpression in glioma cells increased proliferation, migration, and invasion." (PMID 37280594, 2023). "This high expression is positively correlated with the pathological grade of gliomas, suggesting that AQP8 may also be involved in promoting the proliferation and growth of gliomas." (PMID 37280594, 2023). "This indicated that AQP8 affected the proliferation and growth of gliomas." (PMID 37280594, 2023). "However, the mechanism by which AQP8 promotes the proliferation and growth of glioma remains unclear." (PMID 37280594, 2023).
glioma (continued). "Aquaporin 8 (AQP8), which is overexpressed in GBM cells, protects glioma cells from high redox levels to a certain extent by increasing ROS levels, which facilitates the proliferation and growth of GBM cells." (PMID 39639571, 2024). "Therefore, AQP8 may be a potential therapeutic target in gliomas." (PMID 37280594, 2023). "Our results preliminary suggest that AQP8 overexpression alters the ROS/PTEN/AKT signaling pathway, promoting the proliferation, migration, and invasion of gliomas." (PMID 37280594, 2023). "AQP5 have been found expressed highly in primary human glioma cells compared with normal tissue, this is in accordance with the study that reported AQPs (such as AQP1, AQP5 and AQP8) have been observed in high-grade tumors of various tissues." (PMID 28404978, 2017). "This database also showed that the expression of AQP8 in glioma was not high, but there was no control." (PMID 37280594, 2023). "Concerning the MDA level, a high redox level after AQP8 overexpression did not damage glioma cells, but it decreased the level of lipid peroxides by increasing the levels of SOD and GSH." (PMID 37280594, 2023). "Here, the sgRNA system was delivered via lentiviral vectors into glioma A172 and U251 cells that had been previously infected with the CRISPR/Cas9 lentiviral vector and selected by puromycin, which led to the knock-out of AQP8 in the two cell lines." (PMID 35245307, 2022). "In mouse models, glioma cells can overexpress aquaporin 8 (AQP8), which increases ROS levels, resulting in decreased expression of phosphatase and tensin homolog (PTEN) and increased expression of phosphorylated (p)-AKT, thereby promoting the growth and proliferation of gliomas." (PMID 38130720, 2023).
inflammatory bowel disease (7 papers, 2016 to 2023). A spectrum of small and large bowel inflammatory diseases of unknown etiology. "The downregulation of AQP3 and AQP8 was accompanied by an increase in intestinal inflammation and injury, suggesting that both AQP3 and AQP8 may be involved in the pathogenesis of inflammatory bowel disease." (PMID 33673336, 2021). "In the same way, AQP4 and AQP8 are shown to decrease significantly in a mouse model of colitis after exposure to dextran sodium sulfate (DSS), confirming data obtained from clinical investigations in inflammatory bowel disease (IBD) patients." (PMID 27472320, 2016).
leukaemia (6 papers, 2015 to 2023). "Evidence has been provided about the important role of AQP8 in H2O2-mediated redox signaling linked to leukaemia cell proliferation and survival." (PMID 30893772, 2019). "A different study performed by the same group of researchers clarified the effect of AQP8 in the redox balance in human leukemia B1647 cells that constitutively generate VEGF." (PMID 36077720, 2022). "By means of a dimedone-based method for easily monitoring cellular protein sulfenation, our group demonstrated, for the first time, the role of AQP8 on the fine tuning of cysteine oxidation in target proteins involved in leukaemia cell proliferation pathways." (PMID 30893772, 2019). "Therefore, this technique allowed the researchers to clarify the effect of AQP8 on the delicate regulation of cysteine oxidation in target proteins involved in leukemia cell growth pathways." (PMID 36077720, 2022). "Abnormal expression of AQP8 was detected in cervical cancer, leukemia, and esophageal cancer." (PMID 36254092, 2022). "Recent data from our laboratory demonstrated the capacity of specific AQP isoforms (AQP8 and AQP3) to channel NADPH oxidase- (Nox-) produced hydrogen peroxide across plasma membrane in leukaemia cells, affecting downstream redox signaling pathways linked to leukaemia cell proliferation." (PMID 26346093, 2015). "For instance, mammalian Aquaporin 8, which shares ∼33% of amino acid sequence identity with the Drosophila aquaporin channels, controls the entry of NADPH-oxidase derived H2O2 to increase growth factor signaling in human leukaemia B-cells." (PMID 34290589, 2021).
breast carcinoma (5 papers, 2015 to 2025). "Notably, reduced expression of AQP8 has been associated with increased resistance to apoptosis in hepatocellular carcinoma, ovarian cancer, and breast cancer." (PMID 41034734, 2025). "Of these AQPs, reduced expressions of AQP6 or AQP7 were associated with responders to aromatase inhibitors for Luminal A subtype breast cancer, whereas reduced AQP8 expression was associated with responders to anthracycline treatment for Luminal A subtype breast cancer." (PMID 36212456, 2022). "The distinct expression pattern of AQP8 in glioblastoma cells and breast cancer cells can explain why H2O2 is consumed faster by U87 cells than MCF-7 and MDA-MB-231." (PMID 26677750, 2015). "Conversely, increased levels of AQP7 and AQP8 expression correlated with longer survival times, suggesting a possible protective role in cancer that could be analogous to effects of AQPs 4 and 11 in breast cancer." (PMID 32679804, 2020). "The mRNA expression levels of AQP8, AQP9, and AQP10 were upregulated, while those of AQP3, AQP4, AQP5, and especially AQP7, were downregulated in breast cancer based on the Oncomine database." (PMID 36212456, 2022).
cervical carcinoma (5 papers, 2019 to 2025). A carcinoma arising from either the exocervical squamous epithelium or the endocervical glandular epithelium. "AQP8 expression was related to the extent of invasion of cervical cancer cells and was appears to be strongly connected with ERK1/2 activity in cervical carcinoma." (PMID 38336645, 2024). "In HeLa cells, a line derived from a human cervical cancer, AQP8 allows entry of EGF-induced H2O2 exogenously produced, thus amplifying signal transduction and affecting downstream tyrosine phosphorylation." (PMID 30893772, 2019). "Evidence has been reported about AQP8 involvement in human esophageal and cervical cancer, both proceeding via the EGFR/ERK1/2 pathway." (PMID 30893772, 2019).
hepatocellular carcinoma (5 papers, 2015 to 2025). A malignant tumor that arises from hepatocytes. "It has also been reported that AQP8 and 9 expression levels are significantly lower in hepatocellular carcinoma cells than in normal liver cells and that plasma membrane permeability is reduced in HCC." (PMID 39048663, 2024). "For instance, the under-expression of aquaporin AQP8 and 9, in hepatocellular carcinoma, is responsible for the resistance to starvation or TGFβ-induced apoptosis." (PMID 26114386, 2015).
diabetes mellitus (4 papers, 2022 to 2024). A metabolic disorder characterized by abnormally high blood sugar levels due to diminished production of insulin or insulin resistance/desensitization. "In a pancreatic β-cell line, excess H2O2 was linked to a failure of insulin release, potentially significant for diabetes; increased levels of AQP8 had a protective effect, proposed to result from the AQP8-mediated fluxes of H2O2 across mitochondrial and plasma membranes." (PMID 35163313, 2022). "Instead, AQP8-overexpressing cells showed higher proliferative features and increased insulin content, highlighting the role of AQP8 in H2O2 homeostasis in pancreatic β-cells and the development of type-1 diabetes mellitus." (PMID 39125952, 2024).
glioblastoma (4 papers, 2015 to 2024). The most malignant astrocytic tumor (WHO grade IV). "Inhibiting the expression of AQP8 in U87MG cells played an important role in weakening the anti-glioblastoma effect of PSM." (PMID 32922924, 2019). "Thus, the distinct expression pattern of AQP8 in glioblastoma might be responsible for cancer cells being sensitive to high H2O2 concentrations." (PMID 28555065, 2017).
oligohydramnios (4 papers, 2016 to 2021). A lower than normal quantity of amniotic fluid in the amniotic sac as compared to normal values. "In human term fetal membranes and placenta with oligohydramnios, the expression of both AQP8 and AQP9 was significantly decreased in the amnion, while their expressions in the placenta were significantly increased." (PMID 29194396, 2017). "AQP8 and 9 were examined in fetal membrane and placenta in term human pregnancy complicated by polyhydramnios and oligohydramnios." (PMID 29194396, 2017). "Moreover, it was shown that Aquaporin-8 and Aquaporin-9 levels were significantly decreased in amnion and increased in placenta in fetuses suffering from oligohydramnios, further supporting the effect of aquaporins in amniotic fluid levels." (PMID 33902516, 2021). "The expression of aquaporin 8 and aquaporin 9 in amniotic membrane of oligohydramnios group is significantly lower than that of normal amniotic fluid group, however, it has not been shown which lncRNAs regulate the expression of aquaporin 8 and aquaporin 9 in oligohydramnios group." (PMID 32948205, 2020).
adenoma (3 papers, 2012 to 2026). A neoplasm arising from the epithelium. "AQP8 mRNA expression in gastrointestinal tract mostly expressed in normal colonic tissue compared with adjacent adenomas, carcinomas, and cancer cell lines." (PMID 29678898, 2018). "WJW increased/normalized the expression of key epithelial transport proteins involved in Na+/Cl- absorption and water handling, including sodium/hydrogen exchanger 3 (NHE3), epithelial sodium channel (ENaC), downregulated in adenoma (DRA), aquaporin-3 (AQP3), and aquaporin-8 (AQP8)." (PMID 41675980, 2026).
gallstones (3 papers, 2022 to 2026). Solid crystalline precipitates in the biliary tract, usually formed in the gallbladder, resulting in the condition of cholelithiasis. "Previous studies found that chronic alcohol feeding increased bile flow 15, 25, and a recent study reported that AQP8 mediated bile flow and further affected gallstone formation." (PMID 41522337, 2026). "A recent study revealed that hepatic aquaporin 8 (AQP8) facilitates bile flow and its impairment contributes to gallstone formation." (PMID 41522337, 2026).
ovarian carcinoma (3 papers, 2018 to 2025). A malignant neoplasm originating from the surface ovarian epithelium. "In the preent study, we reported for the first time that high AQP8 mRNA expression was associated with favorable OS for all the ovarian cancer patients and advanced stage (III + IV) ovarian cancer." (PMID 29472315, 2018). "AQP6 and AQP9 were reported to be downregulated, whereas AQP8 was unchanged, in ovarian cancer, but their roles remain to be determined." (PMID 32679804, 2020). "Overexpression of AQP8 was significantly correlated with favorable OS in all ovarian cancer patients, HR = 0.85 (0.73–0.98), P=0.024." (PMID 29472315, 2018). "Therefore, high AQP6 and AQP8 mRNA expression may predict a favorable prognosis in ovarian cancer." (PMID 29472315, 2018). "Our results revealed that higher AQP0, AQP1, and AQP4 mRNA expression were correlated with poor OS, whereas higher AQP3, AQP5, AQP6, AQP8, AQP10, and AQP11 showed better OS in ovarian cancer patients." (PMID 29472315, 2018). "Whereas, AQP8 mRNA expression showed not any correlation with all pathological grade of ovarian cancer." (PMID 29472315, 2018).
astrocytomas (2 papers, 2016 to 2022). "We mentioned previously that AQP8 in human astrocytomas is associated with the pathological grade, with higher expression in higher grades." (PMID 28036023, 2016). "AQP8 mRNA expression in human brain astrocytic tumors was found to increase in direct correlation with the pathological grade of astrocytoma." (PMID 36010640, 2022). "AQP8 was also found in the pyriform cortex, hippocampus, dorsal thalamus and globus pallidus and it’s expression was correlated with the grade of astrocytomas." (PMID 28036023, 2016).
clear cell renal cell carcinoma (2 papers, 2022 to 2023). "AQP8 was found to be expressed at lower levels in clear cell renal cell carcinoma (fold change = −3.097), renal pelvis urothelial carcinoma (fold change = −2.198), and papillary renal cell carcinoma (fold change = −2.042) samples than in corresponding normal samples." (PMID 36254092, 2022).
colorectal adenocarcinoma (2 papers, 2022 to 2023). The most common type of colorectal carcinoma. "In conclusion, by integrating WGCNA and differential gene expression analysis, our study screened five important survival-related genes (SLC26A3, GUCA2A, CLCA4, CLCA1, and AQP8) and a 3-gene risk model with the potential to predict the prognosis of colorectal adenocarcinoma." (PMID 35693937, 2022).
colorectal tumors (2 papers, 2016 to 2022). "There was no expression of AQP8 in human colorectal tumors, which indicated a downregulation of the AQP8 gene during tumorigenesis." (PMID 27589719, 2016).